NRP2 (neuropilin 2)
Diseases named in the same sentence as NRP2 in open-access papers (continued):
Sharing a sentence is not in itself a finding about the gene and the disease.
cancer (continued). "Comparison of neuropilin-1 (NRP-1) and neuropilin-2 (NRP-2) expression in alveolar macrophages and interstitial macrophages in lung tissue remote to the cancer nest (physiologically normal lung) (n = 5)." (PMID 26900851, 2016). "Our analysis of HRH1, NRP2, and STX1A expression using the GOBO database corroborated the overexpression of HRH1 and NRP2 in basal-like and HER2-enriched cancer subtypes, while STX1A was overexpressed only in HER2-enriched and luminal B subtypes." (PMID 26673618, 2016). "Neuropilin-2 (NRP2), a family member of NRPs, was shown to regulate autophagy and endocytic trafficking in cancer cells, a function distinctly different from its role as a co-receptor." (PMID 27026195, 2016). "Our results suggest a direct role of NRP2 in epithelial-mesenchymal transition and highlight a cross-talk between neuropilin-2 and TGF-β1 signaling to promote cancer progression." (PMID 21747928, 2011). "Increased expression of neuropilin-2 (NRP-2) has been correlated with enhanced lymphangiogenesis, the process connected to the creation of new lymphatic vessels, which facilitates the dissemination of cancer cells to lymph nodes and distant organs." (PMID 40430075, 2025). "NRPs upregulated in cancer are highly expressed in macrophages, which show tendency towards the phenotypes of M2-type TAMs, suggesting that NRP1 and NRP2 could be more expressed in M2-type TAMs in ccRCC and SKCM, which could be the specific potential target." (PMID 40134439, 2025). "NRP-2 functions as a co-receptor for a variety of growth factors, including VEGF, TGF-β, and HGF, thereby modulating intercellular communication and the migratory behavior of cancer cells." (PMID 40430075, 2025). "In conclusion, miR-200 inhibits the activation of CAFs by targeting NRP2/VEGFR signaling, preventing CAFs from promoting cancer cell motility and invasiveness, reconstructing the ECM, recruiting macrophages and vascular endothelial cells, and facilitating angiogenesis." (PMID 38766528, 2024). "In contrast, aNRP2-10 should potentiate radiation therapy more consistently compared with these radiosensitizers, especially given the high expression of NRP2 in TNBC and the inherent need of antioxidant mechanisms for cancer cells to mitigate radiation-induced ROS." (PMID 39352757, 2024). "We hypothesized that radiotherapy enriches for NPR2-expressing cancer cells within tumors; thus, we screened several TNBC-derived cell lines and observed a positive correlation between radiation dosage and NRP2 cell-surface expression." (PMID 39352757, 2024). "In this scenario, our hypothesis is that SEMA3F and its receptors NRP1 and NRP2 could contribute to DCIS progression to IDC, affecting cancer epithelial cells." (PMID 39138514, 2024). "miR-200 hinders CAF activation via NRP2/VEGFR signaling, limiting cancer cell mobility." (PMID 38766528, 2024). "To verify our hypothesis, we assessed the expression of YAP/TAZ in NRP2-sh CAF-CM-treated cancer cells and found that YAP/TAZ significantly diminished, compared with NRP2-nc CAF-CM-treated cancer cells." (PMID 34826008, 2022). "Taken together, our findings point to a complex interaction between Nrp2 and alternative pro-survival mechanisms in aggressive CRC, which could be exploited in cancer treatment." (PMID 35158941, 2022). "Finally, we identified two cancer stemness-related genes as potential hub biomarkers for COAD, including NRP2 and ADAM12." (PMID 34691191, 2021). "According to the data in the HPA, a subgroup of cancer tissues shows no expression of NRP2 protein while most of the urothelial cancer tissues express high levels of NRP2." (PMID 33918816, 2021). "Neuropilin-2 (NRP2), a multifunctional transmembrane non-tyrosine-kinase glycoprotein, enhances various signal transduction pathways to modulate cancer progression." (PMID 34336654, 2021).
cancer (continued). "Furthermore, NRP2 is required, through WDFY1 (WD-repeat and FYVE-domain-containing protein 1), to activate EGFR endocytosis in cancer cells and to maintain EGFR activities." (PMID 32766254, 2020). "NRP2 is known to regulate ECM adhesion and migration in various cell lines, including human ECs, immune cells and cancer cells." (PMID 32528960, 2020). "Expression of the VEGFR1 and VEGFR3 receptors and NRP1 and NRP2 (data not shown) was not modified in JSRV-induced cancers when compared to normal lungs." (PMID 29137669, 2017). "We observed that NRP2 expression is correlated with vimentin expression and with a lack of E-cadherin expression in these cancer cell lines." (PMID 21747928, 2011). "Our work highlights a cross-talk between NRP2 and TGF-β1 signaling to promote cancer progression." (PMID 21747928, 2011). "Despites several studies pertaining to the role of NRP2 in cancer progression, no substantial evidence established an involvement of this molecular pathway in EMT." (PMID 21747928, 2011). "In cancer tissue, staining of the Nrp2 protein was identified not only in the vascular endothelial cells, but also in the cytoplasm of cancer cells." (PMID 19580679, 2009). "Notably, metabolic stressors present in the TME including hypoxia and nutrient deprivation results in the lysosomal degradation of NRP1, but not NRP2 on endothelial cells and carcinoma cells via autophagy." (PMID 35651620, 2022). "A systemic therapy targeting NRP2 in PCa bone metastasis is unlikely to be specific for cancer cells and could potentially block the NRP2 axis in other cells in the cancer microenvironment." (PMID 33990538, 2021). "In addition, NRP2 upregulators bound with VEGFR2 and integrins can inhibit BMI1 upregulation, which may lead to suppressed cancer development." (PMID 30871059, 2019). "In addition to VEGF, NRP2 can bind many other growth factors such as transforming growth factor-beta (TGF-β), which may contribute to angiogenesis as well as to cancer cell survival and proliferation." (PMID 26673618, 2016). "In particular, NRP2 is also known as a coreceptor for vascular endothelial growth factor (VEGF)-D, which is a well-known lymphangiogenic factor that plays an important role in lymph node metastasis of various human cancers, including papillary thyroid carcinoma (PTC)." (PMID 26030152, 2015). "It has been suggested that NRP1 predominantly expresses in carcinoma cell lines (epithelial origin), including carcinomas of lung, breast, prostate, pancreas, and colon, whereas NRP2 is frequently present in non-carcinoma cell lines derived from melanoma, leukaemia, and neuroblastoma." (PMID 20087344, 2010). "Furthermore, Neuropilin-1 (NRP-1) and Neuropilin-2 (NRP-2) transmembrane proteoglycans, as well as hyaluronic acid (HA) fragments resulting from the hydrolysis of carbohydrate chains in proteoglycans by HYAL hyaluronidase, also display pro-angiogenic properties in several cancer models." (PMID 31157165, 2019). "It has been illustrated that endothelial integrin α5 can bind to neuropilin 2 (NRP2), a multi-functional non-kinase receptor for diverse growth factors expressed on cancer cells, mediating extravasation." (PMID 35884437, 2022). "The majority of the tested cancer types showed positive correlation between the expression of NRP1, NRP2, PLXNC1 and PLXND1, negative correlation between expression of PLXNB1, and the three scores." (PMID 32640719, 2020). "Neuropipin-2 (NRP2), a non-tyrosine kinase receptor frequently overexpressed in various malignancies, including GBM, regulates endosome maturation and EGFR trafficking, supporting the growth and replication of cancer cells." (PMID 34021236, 2021).
infection (22 papers, 2015 to 2025). The state of being infected such as from the introduction of a foreign agent such as serum, vaccine, antigenic substance or organism. "NRP2 plays a similar role during infection of vesicular stomatitis virus (VSV), another well-studied prototypical rhabdovirus." (PMID 40558096, 2025). "Its highest expression was induced by the reactivated from NRP2 phase, showing a 1.2-fold increase compared to log-phase infection and a 3.1-fold increase compared to rNRP1-infected explants." (PMID 41450943, 2025). "Confirming the results obtained with omics data, only EFNB1 and NRP2 overexpression increased infection by Cedar and Lujo pseudotypes, respectively." (PMID 39747691, 2025). "The entry receptors for HCMV are platelet-derived growth factor receptor-α (PDGFRα), which mediates the infection of fibroblasts, and neuropilin-2 (Nrp2), which is essential for endothelial and epithelial cell infection." (PMID 39134803, 2024). "Several of the identified charge clusters in UL128 and UL131A that disrupted endothelial cell infection are located at or near the NRP2 interface." (PMID 35275718, 2022). "Apart from NRP1, its homologous form NRP2 was found to contribute to the infection by certain viruses as well, namely, Lujo virus (LUJV) and human cytomegalovirus (HCMV) which use NRP2 as their viral entry point." (PMID 35955539, 2022). "The pentameric complex targets neuropilin-2 (Nrp2) for efficient infection of epithelial and endothelial cells." (PMID 34200083, 2021). "Soluble Nrp2 protein demonstrated clear reduction of infection for both cell types in comparison to soluble CD46 protein, a result consistent with previous findings." (PMID 31221976, 2019). "On the contrary, Nrp2 knockdown had only a limited effect on MRC-9 infection, which is consistent with the evidence that both Nrp2 and PDGFRα receptors can mediate fibroblast infection, with PDGFRα playing a major role." (PMID 31336680, 2019). "A group of Treg-signature genes (Areg, Arhpag20, Bub1b, Ccl12, Ccr5, Il1r1, Mki67 (Ki67) Ncf1, Nrp2, Tnfrsf9, Tcf19, Uhrf1, and Wnt3) were expressed at higher levels in IFNARfl/fl x Foxp3YFP-Cre mice than WT controls on day 5 Armstrong infection." (PMID 29672594, 2018). "NRP1- and NRP2-targeted knockdown using shRNA infection in these cells significantly decreased PDGFRα and PDGFRβ tyrosine phosphorylation without affecting total PDGFR levels." (PMID 26410366, 2015). "NRP2-GST inhibited ERA-EGFP infection in a dose-dependent manner in all three cell types." (PMID 40558096, 2025). "However, while Nrp-2 was found to play a predominant role for interacting with PC in the infection of epithelial/endothelial cells, both PDGFR-α and Nrp-2 receptors were found to mediate infection of HELF, with PDGFR-α playing a major role." (PMID 36901847, 2023). "In addition, the lower effect of Nrp-2 may be due to the fact that the interaction between the receptor and its ligand occurs within the endosome, so that soluble Nrp-2 cannot inhibit the infection similar to PDGFRα on HELF." (PMID 36901847, 2023). "In contrast, infections with reactivated NRP1 and NRP2 Mtb showed bacterial multiplication within the tissue model at 48 h, with CFU increasing by more than one log (from 1.07 × 106 to 2.11 × 107 CFU/mL)." (PMID 41450943, 2025). "The results showed that the viral titers were significantly higher in NRP2-overexpressing HEK293 cells and N2a cells than in mock-transfected cells at 24 h, 48 h, and 72 h post-infection." (PMID 40558096, 2025). "The 3t3 DC-SIGN cells that acted as the capture cell line in our trans-infection assay were murine fibroblasts, which are known to express high levels of the NRP1 homolog NRP2." (PMID 37766307, 2023). "Following the identification of the PDGFR-α as the TC receptor for infection of HELF, the PC receptor for infection of epithelial/endothelial cells was identified as the Nrp-2." (PMID 36901847, 2023).
infection (continued). "Infection of RAoSMC with shRNAs targeted to rat NRP1 and NRP2 significantly reduced NRP protein expression in RAoSMC." (PMID 26410366, 2015). "This included three receptor–RBP pairs for which mRNA levels were significantly associated with infection in the analyses (Cedar–EFNB1, Lujo–NRP2 and LCMV–DAG1), versus four with no apparent association (HCV–SCARB1, Cedar–EFNA2, SFTSV–MYH9 and rabies–NCAM1)." (PMID 39747691, 2025). "To test whether NRP2 rescues the infection of RABV in DU145 cells, we transduced DU145 cells with a recombinant human adenovirus 5 (Ad) vector expressing the NRP2 cDNA and then assessed RABV endocytosis and infection." (PMID 40558096, 2025). "In particular, VR#2 infection of HELF was almost completely neutralized by anti-PC mAb, (with an IC50 similar to that observed in ARPE-19 and HUVEC), and, to a lesser extent, by Nrp-2." (PMID 36901847, 2023). "The next strongest effect was a 1.5-fold increase to SARS-CoV-2 spike-mediated infection conferred by NRP2, though it similarly simulated infection by VSV-G, which is not processed by furin." (PMID 35895696, 2022). "Nrp2, on the other hand, can be considered a primary entry receptor for pentamer-dependent infection of epithelial and endothelial cells, since HCMV fails to infect these cell types when soluble Nrp2 is present, or when Nrp2 is disrupted or knocked-down using small interfering RNA (siRNA)." (PMID 30544948, 2018).
Cardiovascular Disease (2 papers, 2020 to 2024). "In addition to promoting vascular adhesion and extravasation, Nrp2/α5β1 integrin complexes with fibronectin are implicated in cardiovascular disease-associated NF-κβ signaling with subsequent increases in pro-inflammatory cytokines, chemokines, and adhesion molecules." (PMID 38592275, 2024).
adenocarcinoma (1 paper, 2017). A common cancer characterized by the presence of malignant glandular cells. "Moreover, mRNA expression VEGFD, FGF2 MMP2, NRP1 and NRP2 was decreased in lepidic adenocarcinomas when compared to the normal lungs." (PMID 29137669, 2017). "Interestingly, mRNA expression of the MMP2, NRP1 and NRP2 genes was lower (but not significant) in lepidic-type adenocarcinomas as compared to normal tissues from the same patients." (PMID 29137669, 2017).
inflammation (1 paper, 2022). Aberrant reaction of the microcirculation characterized by movement of fluid and leukocytes from the blood into extravascular tissues. "We previously reported that the immunoregulatory receptor neuropilin‐2 (NRP2) is expressed by murine and human alveolar macrophage (AM) and suppresses lipopolysaccharide (LPS)‐induced neutrophilic airway inflammation." (PMID 34861108, 2022).
kidney (1 paper, 2010). "We verified that NRP1 siRNA transfection did not affect NRP2 expression and NRP2 siRNA transfection did not silence NRP1 expression in both lung A549 and kidney ACHN carcinoma cells." (PMID 20087344, 2010).
neoplastic disorders (1 paper, 2014). "In conclusion, in this paper we have shown that the SEMA3F/NRP2 axis is involved in thymocytes migration and as such should play a critical role in central immune regulation and in the physiopathology of neoplastic disorders of thymocytes." (PMID 25068647, 2014).
overlap syndromes (1 paper, 2024). "Here we show that NRP2 is involved in fibrogenic and osteogenic MSC trajectories and is elevated in MPN, MDS and MPN/MDS overlap syndromes." (PMID 38792002, 2024).
NRP2 also shares sentences with these, for which no sentence is quoted: Obesity (4 papers); astrocytoma (2); B cell lymphoma (2); Cerebral ischemia (2); head and neck squamous cell carcinoma (2); kidney diseases (2); lymphatic malformation (2); neuropathies (2); systemic sclerosis (2); T-cell acute lymphoblastic leukemia (2); type 2 diabetes (2); acute kidney injury (1); adenoma (1); anaplastic carcinomas (1); arteriovenous malformations (1); benign cystadenomas (1); breast ductal carcinoma (1); Burkitt lymphoma (1); cardiac hypertrophy (1); cardiomyopathy (1); CNS tumors (1); cognitive deficits (1); colon adenocarcinoma (1); congenital malformations (1); demyelination (1); diabetic nephropathy (1); dysplasia (1); endocervical carcinoma (1); endometrial cancer (1); focal segmental glomerulosclerosis (1).
A further 34 diseases each share a sentence with NRP2 in 1 paper.